TIMP2 (TIMP metallopeptidase inhibitor 2)
Description:
Complexes with metalloproteinases (such as collagenases) and irreversibly inactivates them by binding to their catalytic zinc cofactor. Known to act on MMP-1, MMP-2, MMP-3, MMP-7, MMP-8, MMP-9, MMP-10, MMP-13, MMP-14, MMP-15, MMP-16 and MMP-19.
Synonyms: CSC-21K; DDC8
Tractability: Antibody: its Gene Ontology location is reachable by antibodies, with high confidence; UniProt places it where antibodies can reach, with medium confidence; UniProt predicts a signal peptide or a membrane-spanning region. PROTAC: ubiquitination databases record sites on it; its protein half-life has been measured.
Gene: Protein-coding gene on chromosome 17 (78,852,977 to 78,925,387, reverse strand). Ensembl gene ENSG00000035862.
Subcellular location: Secreted
Pathways (Reactome):
Extracellular matrix organization: Activation of Matrix Metalloproteinases
Immune System: Neutrophil degranulation
Signal Transduction: TGFBR3 PTM regulation
Gene Ontology:
Molecular function: molecular function inhibitor activity; peptidase inhibitor activity; protease binding; protein binding; zinc ion binding; metalloendopeptidase inhibitor activity
Biological process: negative regulation of metallopeptidase activity; negative regulation of membrane protein ectodomain proteolysis; response to cytokine; response to hormone; negative regulation of proteolysis
Cellular component: extracellular matrix; protease inhibitor complex; extracellular region; ficolin-1-rich granule lumen; specific granule lumen; tertiary granule lumen; secretory granule lumen
Genetic constraint (gnomAD): Loss-of-function variants: 5 observed, 23.46 expected, observed/expected ratio (o/e) 0.21, 90% interval 0.11 to 0.45. The upper end of that interval is the gene's LOEUF score, 0.45, which puts it in group 1 of 6, group 1 being the genes least tolerant of losing a copy. Missense variants: 205 observed, 272.22 expected, observed/expected ratio (o/e) 0.75, 90% interval 0.67 to 0.85. Synonymous variants: 119 observed, 110.6 expected, observed/expected ratio (o/e) 1.08, 90% interval 0.93 to 1.25.
Homologues: Orthologues: chimpanzee TIMP2 (100% identical), macaque TIMP2 (100% identical), mouse Timp2 (98% identical), guinea pig TIMP2 (97% identical), rat Timp2 (82% identical), tropical clawed frog timp2 (78% identical), zebrafish timp2a (72% identical), zebrafish timp2b (59% identical), Drosophila melanogaster Timp (27% identical), Caenorhabditis elegans cri-2 (18% identical). Paralogues in human: TIMP4 (48% identical), TIMP3 (44% identical), TIMP1 (38% identical).
Diseases named in the same sentence as TIMP2 in open-access papers:
TIMP2 is named in the same sentence as 384 diseases in open-access papers, as found by Europe PMC text mining. Sharing a sentence is not in itself a finding about the gene and the disease. The quoted sentences say what the papers report.
breast carcinoma (85 papers, 2003 to 2026). "The association between the variations of these genes and breast cancer has been corroborated by research, such as the identification of the polymorphism of tissue inhibitor of metalloproteinase-2 (TIMP-2) as a risk factor for breast cancer." (PMID 38977630, 2024). "Another study found that single-nucleotide polymorphisms (SNPs) within the TIMP2 gene correlated significantly with breast cancer risk in Han Chinese women." (PMID 36768435, 2023). "TIMP-2 is also associated with tumor malignancy and resistance to chemotherapy in hepatoma, melanoma, and breast cancer." (PMID 35022331, 2022). "High expression levels of TIMP-2 in breast cancer are associated with poor prognosis, whereas low expressions of TIMP-2 in lung cancer are correlated with poor prognosis." (PMID 35022331, 2022). "In this research, we used several large online databases to perform a bioinformatics analysis which was associated with TIMP2 in the clinical characteristics and survival data of breast cancer." (PMID 34678879, 2021). "Although we identified an association between TIMP-2 gene polymorphism and breast cancer, the potential molecular mechanisms are unclear." (PMID 33027062, 2020). "In this study, we evaluated the relationship between TIMP-2 gene rs4789936 polymorphism and the risk of breast cancer in Southern Chinese population." (PMID 33027062, 2020). "Here, we evaluated the relationship between TIMP-2 gene rs4789936 polymorphism and breast cancer risk and prognosis in Southern Chinese women." (PMID 33027062, 2020). "We identified miR-301a-3p as the causal factor that can be transferred by breast cancer-derived EVs to astrocytes and downregulate TIMP-2." (PMID 32481745, 2020). "In the dominant model, after adjustment for age, the individuals with TIMP-2 rs2277698 CT + TT genotype have a 24% lower risk of developing breast cancer than CC genotype (OR = 0.76, 95%CI = 0.60–0.97, p = 0.025)." (PMID 31088428, 2019). "In this study, we found that SNP rs2277698 and haplotype, “TCC” in TIMP-2 was significantly associated with an altered risk of breast cancer." (PMID 31088428, 2019). "Logistic regression analysis was used to assess the influence of TIMP-2 polymorphisms on breast cancer." (PMID 31088428, 2019). "Six single nucleotide polymorphisms (SNPs) within the TIMP-2 gene in 571 breast cancer and 578 healthy control subjects were genotyped through the Agena MassARRAY." (PMID 31088428, 2019). "Of note, we observed that the frequency of the heterozygous variant C/T genotype of TIMP-2 rs2277698 was significantly reduced in breast cancer patients, when compared with healthy group." (PMID 31088428, 2019). "High expression of TIMP2 was associated with bad outcome in colorectal cancer and shortened disease-free and overall survival in human breast cancer." (PMID 30473751, 2018). "We report herein on the effects of a 12-week cycle of doxycycline administration on the circulating levels of the known targets MMP2, MMP9 and their inhibitor TIMP2 in breast cancer patients with bone metastases and their further associations with relevant clinical outcomes." (PMID 36765529, 2023). "However, it is also recognized to have other MMP-independent functions including regulation of tumor angiogenesis, and both increased and decreased expression of TIMP2 has been linked to a more favorable prognosis in breast cancer patients." (PMID 35205651, 2022). "A recent case-control study to assess the association between TIMP-2 polymorphism and breast cancer in Northern Chinese population has suggested that the rs2277698 gene polymorphism is associated with a decreased risk of breast cancer." (PMID 33027062, 2020). "Bioinformatics analysis found that rs4789936 was likely to affect transcription factor binding, motifs, DNase footprint, and DNase peaks; and TIMP-2 was under-expressed in breast cancer, the risk allele of rs4789936 was associated with increased expression of TIMP-2 in peripheral blood samples." (PMID 31088428, 2019).
breast carcinoma (continued). "Very few studies have evaluated polymorphism of TIMP-2 in individuals with breast cancer." (PMID 31088428, 2019). "Genetic screening involving polymorphism of the TIMP-2 gene could provide valuable information for breast cancer susceptibility and identification of high risk patients." (PMID 31088428, 2019). "Importantly, individuals carrying TIMP-2 rs2277698 T allele have a 19% lower risk of breast cancer than individuals with allele C, providing protection (OR = 0.81, 95%CI = 0.67–0.99, p = 0.041)." (PMID 31088428, 2019). "Our study indicated that TIMP-2 rs2277698 was associated with breast cancer susceptibility." (PMID 31088428, 2019). "In conclusion, this study suggests that the TIMP-2 rs2277698 polymorphism is associated with breast cancer in Han Chinese women, and the individuals that carry the CT genotype and “TCC” haplotype may be at reduced risk for breast cancer." (PMID 31088428, 2019). "The present study was conducted to evaluate whether TIMP-2 gene polymorphisms are associated with breast cancer risk in a Han Chinese cohort." (PMID 31088428, 2019). "A previous study found that rs4789936 SNP in TIMP-2 gene may be involved in breast cancer susceptibility and survival in a Shanghai-based population." (PMID 27901480, 2017). "In that study, the variant CT and TT genotypes at the polymorphic site C-1306T of TIMP-2 (rs243865) were associated with a reduced risk of breast cancer (OR = 0.490, 95% CI = 0.033-0.730), compared with the wild-type CC genotype, among 210 breast cancer patients and 290 healthy Tunisian women." (PMID 26872812, 2016). "We also found that TIMP2 was associated with better survival rate of breast cancer patients." (PMID 27504971, 2016). "In addition, Id3 and Timp2 are associated with breast cancer metastasis and mammary gland differentiation." (PMID 27711132, 2016). "Indeed, in some tumors a negative outcome correlates more closely with TIMP-2 than with MT1-MMP levels, and high TIMP-2 levels in primary breast carcinomas are associated with the development of distant metastases." (PMID 26331622, 2015). "Indeed, a negative outcome of certain malignancies correlates more closely with TIMP-2 levels than with MT1-MMP levels, and high TIMP-2 levels in primary breast carcinomas are associated with the development of distant metastases." (PMID 26331622, 2015). "Furthermore, TIMP-1 and TIMP-2 over-expression has been associated with malignant breast tumor behaviour in vivo." (PMID 16168111, 2005). "Besides BRCA1 and BRCA2 mutations that markedly increase breast cancer risk, hundreds of low- and moderate-risk susceptibility variants have been identified, including caspase-8 (rs2293554, rs6723097,), TIMP-2 (rs7501477), and FSCN1 (rs56156320, rs3801004,)." (PMID 39614126, 2025). "Thus, the TIMP-2 gene rs4789936 polymorphism is associated with elevated breast cancer risk and may be an independent prognosis factor in breast cancer patients." (PMID 33027062, 2020). "In conclusion, our data demonstrate that the TIMP-2 gene rs4789936 polymorphism is associated with an elevated risk of breast cancer in Southern Chinese women, and indicate that it might serve as an independent prognosis factor for breast cancer patients." (PMID 33027062, 2020). "This study assessed the impact of intraoperative fluid management on AKI in female breast cancer patients undergoing autologous breast reconstruction, utilizing novel urinary biomarkers (TIMP-2 and IGFBP-7)." (PMID 39048691, 2024). "TGF-β1 phosphorylates p38 MAPK which can induce the expression of MMP-2 and TIMP-2, and increased migration and invasion in breast cancer cells." (PMID 37248432, 2023). "In addition, miR‐4443 regulated by AP002498.1 promotes liver metastasis of breast cancer via microenvironment‐induced TIMP2 loss, and highly expressed lncRNA AP002498.1 may serve as an endogenous sponge to downregulate the expression and inhibit the function of miR‐4443." (PMID 38083905, 2023).
breast carcinoma (continued). "THC treatment decreased the expression level of MMP-9 and MMP-2 in breast cancer cells and increased the expression level of TIMP2." (PMID 36707875, 2023). "For instance, it has been reported an association in breast cancer between high serum levels of TIMP1 and TIMP2 and several parameters indicative of tumoral aggressiveness and lower overall survival." (PMID 36759828, 2023). "Breast cancers are characterized by low expression of TIMP-2, and elevated levels of TIMP-2 are associated with a poor prognosis." (PMID 37176095, 2023). "Further analysis of breast cancer datasets showed that two of these genes which encode a secreted metalloproteinase (PAPPA) and a metalloproteinase inhibitor (TIMP2) were associated with survival outcomes in ILC." (PMID 35205651, 2022). "In the group of patients following breast cancer treatment, the serum levels of TIMP-2 were 85 pg/mL." (PMID 36136069, 2022). "In this study, the levels of TGF-β1, VEGFR-2, and TIMP-2 were determined by the immuno-enzyme serum analysis for patients during the long-term period after breast cancer treatment as potential markers of fibrosis." (PMID 36136069, 2022). "Conversely, the correlation of high TIMP-2 levels with poor prognosis in breast cancer has also been reported." (PMID 36741729, 2022). "In an intergroup comparison, patients after breast cancer treatment showed a statistically significant decrease in the level of TIMP-2 molecules." (PMID 36136069, 2022). "Highly invasive breast cancer cells secreted exosomes with high level of miR-4443 against tissue inhibitors of metalloproteinase 2 (TIMP2); the exosomes mainly accumulated in liver to upregulate MMP-2 and induced liver metastasis." (PMID 36430471, 2022). "We further investigated the expression of TIMP2 among different clinical parameters in breast carcinoma through bc-GenExMiner software, such as age, hormone status, and subtypes." (PMID 34678879, 2021). "Relationships between the expression of TIMP2 and clinical characteristics of breast cancer patients using the bc-GenExMiner database." (PMID 34678879, 2021). "For further, we evaluated the expression of TIMP2 among different clinical parameters in breast carcinoma through bc-GenExMiner software." (PMID 34678879, 2021). "Oncomine databases determined that the expression of TIMP2 was down-regulated in breast cancer, and was related to different types of breast cancer." (PMID 34678879, 2021). "The expression of TIMP2 in different subtypes of breast cancer and compared normal tissues through the Oncomine database." (PMID 34678879, 2021). "The analysis showed that the expression of TIMP2 was down-regulated in breast cancer and ovarian cancer, and up-regulated in gastric cancer, lymphoma, and melanoma." (PMID 34678879, 2021). "In this research, we systematically explored the expression patterns, clinical characteristics, correlations, and prognostic values of TIMP2 in breast cancer." (PMID 34678879, 2021). "In our research, we evaluated the expression and prognostic value of TIMP2 in breast cancer through analyzing various databases including Oncomine, bc-GenExMiner, PrognoScan, UCSC Xena, Kaplan–Meier Plotter, and PPI network." (PMID 34678879, 2021). "In this line, therapeutic upregulation of TIMP-2 reduced the invasiveness of a metastatic breast cancer cell line." (PMID 32560557, 2020). "Together, these findings demonstrated that breast cancer-derived EVs transfer miR-301a-3p to astrocytes, which can then directly target and downregulate TIMP-2 in these cells." (PMID 32481745, 2020). "In our previous study, the highest values were observed for the combination of M-CSF, TIMP-2 and CA 15–3 in all stages of breast cancer group." (PMID 30820752, 2020). "MMP14 and integrin αVβ3 complexes are capable of activating MMP2 activity with the assistance of TIMP2 in breast cancer and melanoma cells." (PMID 32352029, 2020).
breast carcinoma (continued). "Very little is known about the effects of TIMPs on invadopodia formation, although one study in human breast cancer cells suggested TIMP2 is specifically able to decrease the formation of invadopodia." (PMID 31836008, 2019). "This is consistent with a report in breast cancer cells that suggested TIMP2 suppressed invadopodia formation." (PMID 31836008, 2019). "We find that, in lung and breast carcinomas versus normal tissue, the balance between TIMP2 and these known molecular targets is clearly shifted in favor of metalloproteinase expression in tumor tissues." (PMID 31882975, 2019). "Our analysis using the UALCAN database showed that the TIMP-2 gene was under-expressed in breast cancer tissues." (PMID 31088428, 2019). "SP1, which is reported as a transcriptional activator of TIMP-2 gene in breast cancer, was also found as a candidate target gene of miR-130b 41,42." (PMID 31061410, 2019). "Meanwhile, mRNA of TIMP2 in FFPE tissues delivered higher relative expression in biopsy specimens than paired postoperative specimens of 27 breast cancer patients, the difference of ΔCt in paired specimens was 0.38±1.32." (PMID 27504971, 2016). "TIMP-2 was shown to promote breast tumor metastasis by regulating MMP-2-mediated breast cancer cell transmigration through lung microvascular endothelial cells." (PMID 26361584, 2015). "To study the potential role of MT1-MMP and TIMP-2 in AKT activation we used human MCF-7 mammary carcinoma cells stably transfected with MT1-MMP under control by the tetracycline resistance transactivator (Tet-Off)." (PMID 26331622, 2015). "There has been evidence that anti-invasive small molecule SR13179 block breast cancer cell metastasis via up-regulating TIMP2 expression." (PMID 24475196, 2014). "Although no other CMTs study groups assessed the prognostic value of TIMP-2 expression, human breast cancer studies revealed that high levels of TIMP-2 mRNA and TIMP-2 protein are correlated with the development of distant metastasis and decreased DFS." (PMID 23289974, 2013). "In association with TIMP-2, MMP-14 is involved in MMP-2 activation, being also correlated with breast cancer progression." (PMID 22260435, 2012). "Surprisingly, high TIMP-1 and TIMP-2 mRNA levels can predict adverse prognosis and be correlated with tumor aggressiveness in several different human cancers, including breast cancer." (PMID 21726449, 2011). "In this study, the mRNA and protein levels of MMP-2, MMP-9, MMP-13, MT1-MMP and TIMP-2 in benign and malignant mammary tumors were thoroughly analyzed." (PMID 21726449, 2011). "Immunostaining score values for MMPs and TIMP-2 in benign and malignant mammary tumors, expressed as the median (range)." (PMID 21726449, 2011). "Surprisingly, high levels of TIMP-1 and TIMP-2 have also been shown to predict adverse prognosis and correlate with tumor aggressiveness in several different human cancers, including breast cancer." (PMID 19144199, 2009). "Our results confirm that AR are commonly expressed in breast cancer, and are correlated with the expression of some MMPs and TIMP-2." (PMID 18507821, 2008). "One mechanism by which JS-K inhibits breast cancer cell invasion is the upregulation of TIMP-2 production." (PMID 18474097, 2008). "Mice injected with TIMP-2-transfected MDA-MB-231 breast cancer cells had a lower number of osteolytic bone metastases and a higher survival rate than mice injected with nontransfected cells." (PMID 18474097, 2008). "Our results confirm that AR are commonly expressed in breast cancer, and correlate with the expression of some MMPs and TIMP-2." (PMID 18507821, 2008). "Instead, we found surprisingly that breast cancer patients had significantly lower TIMP-2 levels than did healthy controls." (PMID 19662197, 2007). "In a study on 14 patients, Onisto and colleagues report that a high MMP-2/TIMP-2 ratio correlated with lymph node metastases in breast cancer while it predicted a better outcome in another study." (PMID 16776850, 2006).